INTS7 (integrator complex subunit 7)
Description:
Component of the integrator complex, a multiprotein complex that terminates RNA polymerase II (Pol II) transcription in the promoter-proximal region of genes. The integrator complex provides a quality checkpoint during transcription elongation by driving premature transcription termination of transcripts that are unfavorably configured for transcriptional elongation: the complex terminates transcription by (1) catalyzing dephosphorylation of the C-terminal domain (CTD) of Pol II subunit POLR2A/RPB1 and SUPT5H/SPT5, (2) degrading the exiting nascent RNA transcript via endonuclease activity and (3) promoting the release of Pol II from bound DNA. The integrator complex is also involved in terminating the synthesis of non-coding Pol II transcripts, such as enhancer RNAs (eRNAs), small nuclear RNAs (snRNAs), telomerase RNAs and long non-coding RNAs (lncRNAs). May be not involved in the recruitment of cytoplasmic dynein to the nuclear envelope by different components of the INT complex. Plays a role in DNA damage response (DDR) signaling during the S phase.
Synonyms: Int7; C1orf73; DKFZP434B168
Tractability: PROTAC: ubiquitination databases record sites on it; its protein half-life has been measured.
Gene: Protein-coding gene on chromosome 1 (211,940,399 to 212,035,557, reverse strand). Ensembl gene ENSG00000143493.
Subcellular location: Nucleus; Chromosome; Cytoplasm
Subcellular location (Human Protein Atlas): Nuclear bodies
Pathways (Reactome):
Gene expression (Transcription): RNA polymerase II transcribes snRNA genes
Gene Ontology:
Molecular function: protein binding
Biological process: cellular response to ionizing radiation; DNA damage checkpoint signaling; regulation of transcription elongation by RNA polymerase II; RNA polymerase II transcription initiation surveillance; snRNA processing
Cellular component: chromosome; cytoplasm; INTAC complex; integrator complex; nuclear body; nucleus; nucleoplasm
Genetic constraint (gnomAD): Loss-of-function variants: 18 observed, 57.33 expected, observed/expected ratio (o/e) 0.31, 90% interval 0.22 to 0.47. The upper end of that interval is the gene's LOEUF score, 0.47, which puts it in group 2 of 6, group 1 being the genes least tolerant of losing a copy. Missense variants: 564 observed, 700.8 expected, observed/expected ratio (o/e) 0.8, 90% interval 0.75 to 0.86. Synonymous variants: 251 observed, 254.44 expected, observed/expected ratio (o/e) 0.99, 90% interval 0.89 to 1.1.
Homologues: Orthologues: macaque INTS7 (99% identical), dog INTS7 (99% identical), rabbit INTS7 (99% identical), guinea pig INTS7 (97% identical), mouse Ints7 (95% identical), rat Ints7 (95% identical), pig INTS7 (94% identical), chimpanzee INTS7 (92% identical), tropical clawed frog ints7 (86% identical), zebrafish ints7 (76% identical), Drosophila melanogaster defl (37% identical), Caenorhabditis elegans ints-7 (21% identical).
Diseases named in the same sentence as INTS7 in open-access papers:
INTS7 is named in the same sentence as 20 diseases in open-access papers, as found by Europe PMC text mining. Sharing a sentence is not in itself a finding about the gene and the disease. The quoted sentences say what the papers report.
breast carcinoma (2 papers, 2017 to 2025). "Several studies showed that INTS7 is upregulated in several solid tumors, such as cholangiocarcinoma, hepatocarcinoma, cervical squamous cell carcinoma, endocervical adenocarcinoma, and breast cancer." (PMID 40385396, 2025). "Additionally, INTS7 is specifically over-expressed in breast cancer, whereas INTS8 and INTS13 is particularly over-expressed in kidney renal clear cell carcinoma." (PMID 28468258, 2017).
colon cancers (1 paper, 2017). "However, statistically significant differences in the expression of INTS7, INTS8, and INTS13 between tumor and healthy samples were only measured for breast and colon cancers." (PMID 28468258, 2017).
diffuse large B-cell lymphoma (1 paper, 2017). "A global low mutation rate (from 0 to 9.09%) was found, with INTS3 and INTS7 being frequently mutated in lymphoid neoplasm diffuse large B-cell lymphoma (DLBC) (8.16%) and in pancreas adenocarcinoma (PAAD) (9.1%), respectively." (PMID 28468258, 2017).
endometrial carcinoma (1 paper, 2017). A malignant tumor arising from the epithelium that lines the cavity of the uterine body. "In this regard, our pan-cancer investigation of mutations in the INT complex by OncodriveFML revealed that INTS7 and INTS8 can potentially be Mut-driver genes in endometrial carcinoma." (PMID 28468258, 2017).
liver cancer (1 paper, 2024). An epithelial or non-epithelial malignant neoplasm that arises from the liver. "The expression of INTS1, INTS4, INTS7, and INTS8 increased with tumor progression, with all mentioned genes reflecting statistical differences in at least two groups of liver cancer tumor grades comparison." (PMID 38926181, 2024).
metastatic tumors (1 paper, 2024). "The results showed that the expression of INTS1, INTS7, and INTS8 transcripts in both HCC tumors and HCC metastatic tumors was significantly higher than that in normal tissues." (PMID 38926181, 2024). "Moreover, the expression of INTS1, INTS7, and INTS8 transcripts was significantly higher in both primary HCC tumors and HCC metastatic tumors compared to normal tissues, with the expression level in HCC metastatic tumors being significantly higher than in primary HCC tumors." (PMID 38926181, 2024).
thyroid cancer (1 paper, 2017). "Although not significant, a mild reduction of INTS7, INTS8, and INTS13 expression was measured in thyroid cancer samples compared to normal ones." (PMID 28468258, 2017).
uterine corpus endometrial carcinoma (1 paper, 2017). A endometrial carcinoma (disease) that involves the body of uterus. "The INTS7 and INTS8 mutation patterns significantly differed from the background in uterine corpus endometrial carcinoma (UCEC) (INTS7, q-val = 0,182; INTS8, q-val = 0,184)." (PMID 28468258, 2017).
tumor (5 papers, 2017 to 2025). "We then examined the expression of proteins associated with INTS1, INTS3, INTS4, INTS7, and INTS8 in HCC through the Clinical Proteomic Tumor Analysis Consortium (CPTAC) and Human Protein Atlas (HPA) databases." (PMID 38926181, 2024). "The re-analysis of TCGA RNA-Seq data from paired samples (tumor vs. healthy) revealed a robust over-expression of INTS7, INTS8, and INTS13 genes in different tumors." (PMID 28468258, 2017). "A transcriptome analysis of paired (normal and tumor) samples revealed that the transcription of INTS7, INTS8, and INTS13 is significantly altered in several cancers." (PMID 28468258, 2017). "The expression level of INTS7 may correlate with tumor microenvireoment, immunotherapy responsiveness." (PMID 40385396, 2025). "Our analysis indicated that INTS1, INTS4, INTS7, and INTS8 were highly expressed in HCC tissues, with their expressions closely correlated with tumor grade and poor prognosis of HCC patients." (PMID 38926181, 2024). "In this study, we discovered that INTS1, INTS4, INTS7, and INTS8 exhibited high expression levels in tumor tissues compared to normal tissues in both the UALCAN and GEPIA2 systems (P < 0.05)." (PMID 38926181, 2024). "Therefore, we analyzed the differential expression of INTS1, INTS3, INTS4, INTS7, and INTS8 in normal, further tumor, and metastatic HCC tissues using the TNM plotter." (PMID 38926181, 2024). "Subsequently, we investigated whether the expression levels of INTS1, INTS4, INTS7, and INTS8 correlated with patient tumor staging." (PMID 38926181, 2024). "Conversely, INTS7 and INTS8 exhibit oncogenic properties and may stimulate tumor growth, migration, and invasion." (PMID 37537630, 2023).
cancer (4 papers, 2017 to 2024). A tumor composed of atypical neoplastic, often pleomorphic cells that invade other tissues. "Previous studies have reported that the transcription of the human INTS7 gene was significantly altered in several cancers, and INTS7 depletion was shown to induce cell-cycle arrest." (PMID 34880777, 2021). "Integrator complex subunit 7 (INST7) has ever been identified as highly mutated and significantly overexpressed in diverse human cancers." (PMID 34880777, 2021). "Furthermore, we observed that the co-expressed genes of INTS1, INTS4, INTS7, and INTS8 were involved in diverse processes associated with cancer development, underscoring their significant role in HCC progression." (PMID 38926181, 2024). "Despite the fact that we could not establish them as cancer drivers, INTS7 and INTS8 genes were highly mutated in specific cancers." (PMID 28468258, 2017). "Remarkably, despite not being able to definitely establish INTS7 and INTS8 as cancer driver genes, the transcriptome analysis of RNA-Seq paired samples revealed that these two genes, together with INTS13, are the most deregulated across cancers." (PMID 28468258, 2017).
infection (1 paper, 2017). The state of being infected such as from the introduction of a foreign agent such as serum, vaccine, antigenic substance or organism. "Moreover, upon infection, INTS7 co-localizes with viral DNA factories, while Rhino re-distributes from the nucleus into the cytoplasm." (PMID 28467896, 2017).
INTS7 also shares sentences with these, for which no sentence is quoted: Alzheimer disease (1 paper); cannabis dependence (1); cervical squamous cell carcinoma (1); cholangiocarcinoma (1); endocervical adenocarcinoma (1); lymphoid neoplasm (1); nicotine dependence (1); osteoporosis (1); Parkinson disease (1).